INS (insulin)
Diseases named in the same sentence as INS in open-access papers (continued):
Sharing a sentence is not in itself a finding about the gene and the disease.
Hyperglycemia (continued). "However, due to the various variability, uncertainty and complex glucose dynamics, optimizing the doses of insulin delivery to minimize the risk of hyperglycemia and hypoglycemia is still an open problem." (PMID 32899979, 2020). "However, chronic hyperglycemia will result in glucotoxicity in the beta cells; glucotoxicity will cause dysfunction and changes in the beta-cell mass, leading to a decrease in insulin secretion." (PMID 33281368, 2020). "We previously observed varied responses of 35 biomarkers to acute hyperglycemia in men with prediabetes, while other studies also observed inconsistent associations of selected adipocytokines with acute (first phase) insulin response and glycohemoglobin A1c (HbA1c) in diabetic individuals." (PMID 33233515, 2020). "Nevertheless, assessing low glucose tolerance (HbA1c, peptide C, insulin) early, during the acute condition associated with stress hyperglycemia, and in dynamics could provide more data about low tolerance glucose status." (PMID 32120784, 2020). "IGF2BP2 variations were also associated with decreased insulin secretion and hyperglycemia." (PMID 32329795, 2020). "In response to injury, the neuroendocrine system increases secretion of counterregulatory hormones that promote rapid mobilization of nutrient stores, impair insulin action, and ultimately cause hyperglycemia, a condition known to impair recovery from injury in the clinical setting." (PMID 33097799, 2020). "We used EPIPAGE-2, a national population-based prospective cohort study representing a large variation of practices, to examine the impact of strategies to avoid or reduce hyperglycemia on the risk of ROP by studying the association between use of insulin therapy and severe ROP." (PMID 33306685, 2020). "Here we report that leptin receptors (LEPRs) in neurons expressing Cre recombinase driven by a short fragment of a promoter region of Ins2 gene (RIP-Cre25Mgn neurons) are required for central leptin signaling to reverse dyslipidemia, thereby hyperglycemia in insulin-deficient mice." (PMID 33071988, 2020). "DM is a metabolic disease caused by abnormal insulin function and characterized by hyperglycemia." (PMID 32566690, 2020). "Hyperglycemia is caused by the impaired production of insulin and resistance of insulin." (PMID 32076626, 2020). "However, insulin is indicated during pregnancy to treat maternal hyperglycemia and reduce the risk of fetal macrosomia if serial ultrasound biometry suggests that the fetus has not inherited the maternal GCK mutation." (PMID 33292863, 2020). "Inhibited upregulation of adiponectin secretion and/or blunted suppressive effect of insulin due to hyperglycemia or exogenous insulin administration may have caused the decrease in adiponectin levels." (PMID 31905496, 2020). "Surgery can cause an immunosuppressive effect in the early postoperative stage due to surgical stress and trauma, effects of general anesthetic agents, intraoperative hypothermia, intraoperative blood loss and transfusion, and hyperglycemia due to postoperative insulin resistance." (PMID 32309426, 2020). "Moreover, further research on the mechanism underlying the effects of pasireotide on insulin synthesis and secretion, and insulin sensitivity, in CD patients will help to develop specific guidelines for managing pasireotide-induced hyperglycemia in the future." (PMID 31313243, 2020). "By treating with insulin, the contribution of hyperglycemia versus other risk factors may be assessed." (PMID 32832565, 2020). "Therefore, a reduction in insulin secretion causes body weight loss, hyperglycemia, and dyslipidemia." (PMID 31100973, 2019). "This might be the fact that the hyperglycemia was linked with a genetically dysfunction of beta cell and familial predisposition to insulin secretory defects." (PMID 31519151, 2019). "Since operating antagonizes insulin, surgery may predispose people to hyperglycemia which reduces the functional ability of leukocytes to fight infection." (PMID 35240760, 2019).
Hyperglycemia (continued). "On the other hand, insulin is a high-alert medication and errors in its administration may cause serious hypoglycemia and hyperglycemia, seizures, coma, ketoacidosis, and even death." (PMID 30907735, 2019). "Hyperglycemia is associated with increasing levels of six amino acids (alanine, isoleucine, leucine, valine, phenylalanine, and tyrosine) and with decreasing levels of histidine and glutamine; these associations were explained by insulin sensitivity." (PMID 31314811, 2019). "However, a rise in intramyocellular lipids is associated with impaired insulin action and reduced glucose uptake by muscle cells, which in turn largely contributes to hyperglycemia." (PMID 31623226, 2019). "Furthermore, therapy with GLP1-RA is associated with a potentiation of glucose induced insulin secretion and a modest weight loss and as a result it effectively reduces hyperglycemia in patients with T2DM." (PMID 31164926, 2019). "Although detailed information is available on the molecular mechanisms underlying hyperglycemia and lipid accumulation, their relations with the presumed insulin signaling and FoxO1, remain unknown." (PMID 31246177, 2019). "One of the classical symptoms of pheochromocytoma crisis is hyperglycemia that might be caused by increased insulin resistance in peripheral tissues and impaired insulin secretion." (PMID 30609924, 2019). "Furthermore, many factors such as matrix metalloproteinase activity, hyperglycemia and insulin administration are associated with increased permeability of the BBB." (PMID 31067852, 2019). "Chronic exposure to HFD is often associated with hyperglycemia due to insulin insensitivity." (PMID 31565046, 2019). "Thus, when insulin action is normal, hyperglycemia occurs when absolute insulin secretion is deficient." (PMID 31776781, 2019). "In addition, smoking increases the risk of hyperglycemia by inhibiting insulin sensitivity and resistance." (PMID 30658463, 2019). "These factors impair insulin release and consequently cause hyperglycemia." (PMID 31871617, 2019). "Additionally, normal microvascular function is necessary for physiological insulin-mediated glucose disposal and glucose-induced insulin secretion, highlighting that association between ED and hyperglycemia in T2D is bidirectional." (PMID 31739614, 2019). "In addition, due to their lack of specificity, IGF-1R tyrosine kinase inhibitors are associated with hyperglycemia because of interference with insulin signaling." (PMID 30692633, 2019). "It is clear that hyperglycemia is associated with the pro-inflammatory state, which is also true for low-grade inflammatory conditions due to over-nutrition, where insulin exerts pro-inflammatory effects and presumably contributes to the pathogenesis of these diseases." (PMID 31817857, 2019). "Nonetheless, both strategies face different disadvantages and must be balanced against individual therapies: reducing bolus and/or basal insulin and its association with hyperglycemia might imply a harmful impact on micro- and macrovascular complications." (PMID 31174360, 2019). "Among the factors associated with ICU weakness, hyperglycemia has been considered important, as insulin therapy might be an attenuating factor of muscle loss through its anabolic properties." (PMID 31284633, 2019). "As such the inability of male mice and rats to preserve insulin responses in the face of elevated blood glucose levels may leave them susceptible to AP-induced hyperglycemia." (PMID 31555747, 2019). "Thereafter, they develop hyperglycemia due to loss of glucose-induced insulin secretion." (PMID 30415925, 2019). "The evaluation of GV helps to comprehend and assess the effect of the patient’s timely actions on the hypoglycemia and hyperglycemia incidence by associating out-of-target BG levels with patient-specific factors, such as insulin dosage, other medication, meals, activity, stress, and illness." (PMID 31042157, 2019).
Hyperglycemia (continued). "However, these mice presented increased susceptibility to visceral obesity, hyperglycemia, and impaired insulin secretion whenever they started a high-fat diet." (PMID 31817436, 2019). "Everolumus, for example, can cause hyperglycemia by decreasing insulin production." (PMID 31586989, 2019). "In addition, impaired insulin release and/or action causes hyperglycemia through increasing hepatic glucose output and decreasing glucose utilization by peripheral tissues." (PMID 31887984, 2019). "Bolus insulin dose reductions are often linked to pre-exercise hyperglycemia that might impact on improvements in glycemic control (HbA1c) and potentially increase the risk of ketoacidosis related to insulin omissions." (PMID 31174360, 2019). "Chronic hyperglycemia and elevated free fatty-acids negatively impact β-cell function and insulin secretion, but mechanisms underlying secondary loss of insulin remain unclear." (PMID 31061431, 2019). "However, long period of maternal hyperglycemic environment will stimulate pancreatic β-cell proliferation, insulin secretion and hyperglycemia on fetus, and cause serious effects on the endocrine system and development of various organs of the fetus." (PMID 31362999, 2019). "Moreover, due to the hyperglycaemia and oxidative stress, the impairment of insulin release from granules by beta cells and loss of pancreatic mass were observed." (PMID 30720717, 2019). "The beta cells in T2DM individuals tend to secrete more insulin in order to fight against hyperglycemia, this increased insulin secretion may cause intensive calcium uptake in beta cells thus lowering the level of serum calcium." (PMID 31781028, 2019). "Insulin therapy is often very effective at treating the hyperglycemia associated with the resistance; however, the effects of the supplemental insulin on blood pressure (BP) and the cardiovascular-renal system in already hyperinsulinemic subjects are incompletely understood." (PMID 30249002, 2018). "However, administration of dexamethasone is known to cause various adverse effects including hyperglycemia which requires insulin therapy." (PMID 29454372, 2018). "The mechanism proposed to explain these phenotypes suggests that there is a mild beta cell defect caused by some mutations that may be compensated transiently, and that the hyperglycemia may present again in periods of increased insulin requirements." (PMID 28943514, 2018). "While our data demonstrate that cervical VNS can cause hyperglycemia through inhibition of glucose‐induced insulin release, mechanisms other than inhibition of insulin or stimulation of glucagon release likely contributed to the elevated fasted blood glucose levels with VNS." (PMID 30569658, 2018). "Corticosteroids have been shown to cause hyperglycaemia through several mechanisms: induction or worsening of preexisting insulin resistance, increasing liver gluconeogenesis whilst decreasing insulin secretion, and, in the long term, by stimulating appetite and subsequent weight gain." (PMID 29623219, 2018). "Our results, in which the HOMA2 %B decreased and the edema score of pancreases increased after the chemotherapy, supported the hypothesis directly, that the hyperglycemia might be caused by the decrease of insulin secretion in pancreatic islets." (PMID 29338697, 2018). "The FFA could also destruct pancreatic β cells to reduce insulin secretion, which lead to hyperglycemia and caused body damage." (PMID 29433562, 2018). "Additionally, small HDL particles were previously associated with reduced insulin sensitivity and hyperglycemia." (PMID 29321013, 2018). "T2DM is characterized by hyperglycemia caused by insulin resistance and/or abnormal insulin secretion, either of which may predominate." (PMID 29849912, 2018). "Moreover, mice that developed hyperglycaemia showed glucagon positivity but a loss of insulin positivity in a number of islets, indicating destruction of the insulin-producing beta cells." (PMID 29151123, 2018).
Hyperglycemia (continued). "Maternal hyperglycemia is associated with the increased placental transfer of glucose, resulting in fetal hyperglycemia and increased insulin production, with the resultant effect being an increase in insulin-mediated fetal growth, or macrosomia." (PMID 29695082, 2018). "It is know that alloxan causes hyperglycemia, however, hypoglycemia may occur within 48 hours, presumably due to release of preformed insulin from damaged beta cells." (PMID 30622608, 2018). "The practice of cycling PN may also be associated with stress hyperglycemia, most likely due to impaired insulin secretion." (PMID 30460219, 2018). "Indeed, smoking reduces insulin sensitivity and induces insulin resistance enhancing cardiovascular risk factors such as elevated plasma triglycerides, decreased high-density lipoprotein cholesterol and hyperglycemia." (PMID 29989097, 2018). "The variables identified here that were associated with hyperglycemia or predictive of the use of basal-bolus insulin therapy could be used to construct guidelines on modifying treatment algorithms for surgical practitioners." (PMID 29255628, 2018). "Chronic extracellular hyperglycemia causes elevated production of ROS by the mitochondrial electron-transport chain and thus leads to disturbed cell redox state and abnormal expression of genes of insulin sensitivity." (PMID 30050652, 2018). "In the present study, insulin-mediated tight glucose control, after surgery, doubled glutathione synthesis rates in erythrocytes, as compared to the condition of relative insulin deficiency with moderate hyperglycemia." (PMID 29300728, 2018). "Not only does the rapid absorption profile associated with rapid-acting insulin preparations allow for a more effective correction of incidental hyperglycaemia but also the preparations can be injected at a shorter time prior to meal intake, increasing the flexibility of their use." (PMID 30116732, 2018). "It is well accepted that chronic hyperglycemia causes insulin resistance in skeletal muscles." (PMID 30538991, 2018). "Thus, hyperglycemia associated with disturbances in insulin action results from both low glucose disposal and unrepressed glucose production." (PMID 29768504, 2018). "This is a major point, because hypertriglyceridemia may serve as a marker of reduced insulin production or activity and may indicate the presence of lipotoxicity, which can lead to beta cell loss, especially in the presence of hyperglycemia." (PMID 30327785, 2018). "In the present study, increase of insulin secretion by DPP-4 inhibitors via night hyperglycemia might cause fasting hypoglycemia in the morning." (PMID 30285859, 2018). "This may also lead to partial or complete loss of insulin synthesis and thus the development of hyperglycemia (Akolade, Usman, Okereke, & Muhammad, 2014)." (PMID 30258612, 2018). "Further, transient hyperglycemia might cause epigenetic changes, inducing cellular metabolic memory, increasing insulin resistance and pancreatic β-cell dysfunction and apoptosis." (PMID 29477146, 2018). "Hyperglycemia and impaired insulin secretion are the main cause of enhanced production of AGES." (PMID 28781721, 2017). "In addition, microvascular dysfunction can cause hyperglycemia by impairing the timely access of glucose and insulin to their target tissue and by impairing insulin secretion." (PMID 29077770, 2017). "Hyperglycemia and decreased levels of insulin have been considered major factors to cause DR." (PMID 29064407, 2017). "In this study insulin treatment alone showed reduction in cold allodynia condition which might be linked to the reduction of hyperglycemia." (PMID 28381989, 2017). "Thus, insulin resistance in the liver, which is the reduced sensitivity to insulin in the liver, causes gluconeogenesis and hyperglycemia." (PMID 29065507, 2017). "Whether alterations in these signals are causes or consequences of altered insulin signalling and hyperglycemia is not clearly known." (PMID 28767672, 2017).
Hyperglycemia (continued). "Defective insulin responsiveness occurs as a consequence of genetic susceptibility and effects of extracellular agents, among which the excess of free fatty acids, chronic hyperglycemia and hyperinsulinemia are currently of particular research interest." (PMID 28236091, 2017). "GLP-1 receptor agonists stimulate glucose-medicated insulin secretion, suppress glucagon secretion, delay gastric emptying, and decrease appetite, thus explaining the considerable effect of these drugs on postprandial hyperglycemia and weight loss." (PMID 28115994, 2017). "Patients treated with therapeutic hypothermia (TH) and continuous insulin may be at increased risk of hyperglycemia or hypoglycemia, particularly during temperature transitions." (PMID 29075530, 2017). "Severe hyperglycemia in these mice is due to the loss of insulin-producing beta cells." (PMID 29018279, 2017). "This alteration was caused by a metabolic imbalance due to insulin deficiency; since insulin replacement therapy in STZ-induced diabetic rats (sufficient to attenuate hyperglycemia) produced glomeruli with extracellular adenosine levels similar to those found in non-diabetic animals." (PMID 28842605, 2017). "Changes in maternal metabolic state are directly transmitted to the fetus: for example, maternal hyperglycemia in pregnant women induces hyperglycemia and elevated insulin levels in the fetus, thus increasing the risk for complications in infancy and later life." (PMID 28744256, 2017). "Exaggerated insulin dose reductions can cause hyperglycemia and may lead to development of ketosis during physical activity." (PMID 28662684, 2017). "Diabetic ketoacidosis (DKA) represents a profound insulin deficient state leading to hyperglycemia (>200 mg/dl) and acidosis (serum pH < 7.3, HCO3 < 15 mEq/L), along with accumulation of keto-acids in the blood, dehydration, electrolyte loss, and hyperosmolality." (PMID 28376867, 2017). "Our results suggest that the enhanced insulin-response to glucose observed in CX-4945-treated old mice could be partially induced by the hyperglycemia associated with CK2-inhibition in several tissues." (PMID 29242563, 2017). "Previous studies have reported that rapamycin, an mTOR inhibitor, may cause hyperglycemia by inhibiting insulin secretion or insulin resistance." (PMID 28781589, 2017). "On the contrary, in our cohort, the independent association between insulin therapy and an increase in c-peptide during hyperglycemia supports a previous hypothesis that exogenous insulin may stimulate beta-cell function (beta-cell recruitment)." (PMID 28497374, 2017). "Its inhibition causes a decrease in both postprandial hyperglycaemia and hyperinsulinaemia, and thereby may improve sensitivity to insulin and alleviate the stress on β-cells." (PMID 28045450, 2017). "The STZ-induced diabetes type 1 in the rats in this study was characterized by body weight loss, hyperglycemia, decreased plasma insulin level, renal dysfunction and renal histological changes which were shown to have a correlation with an increase in renal oxidative stress." (PMID 29051569, 2017). "Hepatic insulin signaling modulates glucose output to maintain serum glucose hemostasis through activating insulin receptor substrate (IRS)-1/2/PI3K/Akt pathway; this pathway impairment causes hyperglycemia and compensatory hyperinsulinemia, cooperatively preceding systemic insulin resistance." (PMID 28353649, 2017). "A deficiency in insulin results in hyperglycemia with metabolic disturbances of biomolecules." (PMID 28333074, 2017). "Indeed, we found myocardial ischemia per se caused hyperglycemia through hepatic insulin signaling blunting, besides that hyperglycemia resulted in exacerbation of myocardial I/R injury, which formed a vicious cycle leading to poor outcomes." (PMID 28038474, 2017).